RNU6-541P (RNA, U6 small nuclear 541, pseudogene)
Gene: Small nuclear RNA gene on chromosome 14 (31,142,939 to 31,143,048, forward strand). Ensembl gene ENSG00000207440.
Homologues: Orthologues: chimpanzee U6 (99% identical), macaque U6 (85% identical), pig U6 (69% identical). Paralogues in human: RNU6-116P (85% identical), RNU6-1060P (84% identical), RNU6-15P (84% identical), RNU6-19P (84% identical), RNU6-33P (84% identical), RNU6-1 (83% identical), RNU6-2 (83% identical), RNU6-20P (83% identical), RNU6-21P (83% identical), RNU6-39P (83% identical), RNU6-3P (83% identical), RNU6-455P (83% identical), and 1286 more.